COL11A1 (collagen type XI alpha 1 chain)
Diseases named in the same sentence as COL11A1 in open-access papers (continued):
Sharing a sentence is not in itself a finding about the gene and the disease.
ovarian carcinoma (continued). "Furthermore, COL11A1-knockdown human ovarian cancer cell lines are defective in inducing peritoneal metastasis and lung colonization when inoculated into mice." (PMID 33668097, 2021). "We, and others, have shown in human ovarian cancer cell lines and xenograft mouse models that COL11A1 is not only associated with poor response to cisplatin, but also confers cisplatin resistance though multiple mechanisms." (PMID 33668097, 2021). "Besides, COL11A1 expression has been suggested as a promising marker for invasive breast lesions and ovarian cancer and has a positive correlation with cisplatin treatment." (PMID 33987034, 2021). "Indeed, TGF-β1 signaling pathway can also regulate COL11A1 expression through transcription factor NF-Y in human ovarian cancer cell lines in vitro and in vivo." (PMID 33668097, 2021). "show that COL11A1 expression can be elevated in intratumoral vasculature in ovarian cancer." (PMID 33668097, 2021). "It has been reported that inhibition of Akt with SC66 reduces expression levels of COL11A1 in ovarian cancer cells 70, indicating that Akt signaling might induce expression of COL11A1." (PMID 33531986, 2021). "The overexpression of COL11A1 has also been found in radioresistant ovarian cancer samples." (PMID 34944877, 2021). "In addition, using a Human Protein Kinase Array, we demonstrated that AMPK was one of the phosphoproteins upregulated in response to culturing ovarian cancer cells on COL11A1." (PMID 32312965, 2020). "Only AZD5363 could inhibit COL11A1 mRNA and promoter activity, which are important factors in Akt regulation and chemoresistance in ovarian cancer." (PMID 32194423, 2020). "Therefore, we asked if COL11A1 also increases the uptake of extracellular fatty acids to promote FAO in ovarian cancer cells." (PMID 32312965, 2020). "Given our initial observation that FAO is upregulated in cisplatin-resistant variant of A2780 cell line (A2780cis), we sought to test whether FAO inhibition can attenuate COL11A1-induced cisplatin resistance in ovarian cancer cells." (PMID 32312965, 2020). "Furthermore, we discovered that COL11A1 upregulates de novo fatty acid synthesis to derive fatty acids for oxidation in ovarian cancer cells." (PMID 32312965, 2020). "In addition, COL11A1 interferes with anti-cancer drug-induced apoptosis in ovarian cancer cells by upregulating TWIST1-mediated Mcl-1 expression." (PMID 30975980, 2019). "We also elucidated the mechanisms by which COL11A1 promotes cancer cell sensitivity to anticancer drugs and we observed that, in ovarian cancer cells, chemoresistance developed via activation of the Akt/c/EBPβ pathway in concert with attenuated PDK1 ubiquitination and degradation." (PMID 30975980, 2019). "We further verified whether SC66 would overcome COL11A1-mediated chemoresistance in ovarian cancer cells." (PMID 30975980, 2019). "In addition, COL11A1 promotes ovarian cancer cell chemoresistance through the activation of signaling pathways such Akt and PDK1 pathways." (PMID 28754000, 2017). "Of note, previous reports showed that COL11A1 elevates phosphorylated Akt in ovarian cancer cells by stabilizing PDK1, and FLT4 participates in the induction of phosphorylation of extracellular signal-regulated kinase (ERK) 1/2 as well as in the proliferative and migratory ability of SG-2 cells." (PMID 28555007, 2017). "COL11A1 expression has been demonstrated to be high in cisplatin-resistance ovarian cancer cells." (PMID 28754000, 2017). "For instance, VCAN and POSTN were demonstrated in vitro to be involved in ovarian cancer invasion induced by TGF-β signaling, and COL11A1 was shown to increase continuously during ovarian cancer progression and to be highly overexpressed in recurrent metastases." (PMID 27843486, 2016). "Here, we further showed that COL11A1 could increase phosphorylated Akt in chemoresistant ovarian cancer cells by stabilizing PDK1 protein." (PMID 26087191, 2015).
ovarian carcinoma (continued). "We identified COL11A1 as a candidate biomarker of chemoresistance in ovarian cancer." (PMID 26087191, 2015). "Our results suggest that although cisplatin and paclitaxel exert their killing effects on ovarian cancer cells, they simultaneously induce the emergence of a subpopulation of cancer cells with activated Akt/c/EBPβ/COL11A1 signalling, which confers chemoresistance." (PMID 26087191, 2015). "In the present study, we elucidated the mechanisms by which COL11A1 promotes cancer cell sensitivity to anticancer drugs, and we observed that, in ovarian cancer cells, chemoresistance developed via activation of the Akt/c/EBPβ pathway in concert with increased PDK1 degradation." (PMID 26087191, 2015). "Collectively, these results indicate that PDK1 stabilization in chemoresistant ovarian cancer cells could be increased by COL11A1." (PMID 26087191, 2015). "Here, we have organized and summarized recent developments regarding the interactions between COL11A1 and intracellular signaling pathways and selected therapeutic agents targeting COL11A1, as these indicate its potential as a target for treatment of cancers, especially epithelial ovarian cancer." (PMID 35847935, 2022). "It is tempting to speculate that a possible mechanism by which ovarian cancer cells stimulated by COL11A1 maintain resistance to cisplatin involves upregulation of total and phosphorylated HSP27, which in turn activates NFkB and subsequentially leads to an increase in IAP expression." (PMID 34638339, 2021). "However, it is poorly understood how COL11A1 promotes ovarian cancer cisplatin resistance." (PMID 34638339, 2021). "Interestingly, HSP27 knockdown or inhibition stimulates ovarian cancer cells to upregulate fatty acid oxidation (FAO) for survival and cisplatin resistance, and dual inhibition of HSP27 and FAO synergistically kills ovarian cancer cells that are cultured on COL11A1." (PMID 34638339, 2021). "In particular, in aggressive ovarian cancer, COL11A1 expression is limited to the αSMA-positive CAFs adjacent to the tumor periphery (<1 mm from the epithelial cells) or within the tumor, suggesting that COL11A1 expression can be stimulated in CAFs when they are in close proximity to cancer cells." (PMID 33668097, 2021). "Therefore, we tested whether COL11A1 engages the same receptors to upregulate FAO in ovarian cancer cells." (PMID 32312965, 2020). "Therefore, we propose that blocking FAO might serve as a promising therapeutic target to treat ovarian cancer, particularly cisplatin-resistant recurrent ovarian cancers which typically express high levels of COL11A1." (PMID 32312965, 2020). "Therefore, we questioned whether AMPK is activated by COL11A1 to upregulate FAO in ovarian cancer cells." (PMID 32312965, 2020). "Therefore, targeting FAO using these drugs might be a promising therapeutic strategy for cisplatin-resistant recurrent ovarian cancer, which often overexpress COL11A1." (PMID 32312965, 2020). "In addition to an increased expression, some genes were also downregulated by the overexpression of FGF14, such as COL11A1 which encodes the α1 chain of collagen XI and MUC16, a well-established biomarker used to monitor the progression and recurrence of ovarian cancer." (PMID 32707902, 2020). "We suggest that SC66 may have potential for use in patients with COL11A1-positive ovarian cancer." (PMID 30975980, 2019). "In addition, COL11A1 is preferentially elevated in cisplatin-resistant ovarian cancer cells." (PMID 26087191, 2015). "Similar to its role in ovarian cancer, in addition to the regulation of invasion, migration and proliferation of tumor cells in NSCLC, COL11A1 induces the cisplatin resistance of tumor cells through overexpression and activating Smad signaling pathway." (PMID 36160004, 2022). "Previous studies reported that COL11A1 modulates the NF-κB/IGFBP2/TGF-β3 cascade to promote EMT and activate the CAFs in ovarian cancer." (PMID 36266702, 2022).
ovarian carcinoma (continued). "In summary, this data suggests that COL11A1 induces both total and phosphorylated HSP27 in ovarian cancer cells." (PMID 34638339, 2021). "In this study, we report that COL11A1 upregulates HSP27 expression and activity through DDR2/integrin α1β1-Src-Akt signaling to induce cisplatin resistance in ovarian cancer cells." (PMID 34638339, 2021). "It has been shown that COL11A1-matrisome signature positively correlates with Treg and TH2 signatures and poor clinical outcome in ovarian cancer specimens." (PMID 33668097, 2021). "In summary, COL11A1 transcription is driven by the transcription factors c/EBPβ, NF-Y, Sp1, and B-myb, and growth factors like TGF-β1 in ovarian cancer, sarcoma cells, and lung cancer cells." (PMID 33668097, 2021). "Through receptor knockdown and inhibitor experiments, we demonstrated that COL11A1 significantly upregulates HSP27 phosphorylation and expression via DDR2/integrin α1β1 and Src/Akt signaling in ovarian cancer cells." (PMID 34638339, 2021). "We have previously reported that COL11A1 activates Src-Akt signaling through the collagen receptors discoidin domain receptor 2 (DDR2) and integrin α1β1 to confer cisplatin resistance to ovarian cancer cells." (PMID 34638339, 2021). "A great example is collagen type XI alpha 1 (COL11A1), which is a new biomarker of cisplatin resistance in ovarian cancer." (PMID 33809784, 2021). "We previously published that COL11A1 engages DDR2 receptor tyrosine kinase and α1β1 integrin on cell surface to transduce downstream signaling in ovarian cancer cells." (PMID 32312965, 2020). "Collectively, these results suggest that COL11A1 activates Src and Akt to upregulate FAO in ovarian cancer cells." (PMID 32312965, 2020). "In particular, we showed that COL11A1, a collagen subtype specifically overexpressed in cisplatin-resistant ovarian cancer, upregulates FAO to promote cisplatin resistance in ovarian cancer cells." (PMID 32312965, 2020). "Interestingly, DDR2 knockdown significantly abrogated COL11A1-induced FASN overexpression while ITGA1 knockdown only slightly reduced FASN expression (data not shown), suggesting that DDR2 might be the predominant receptor that mediates COL11A1-induced FASN expression in ovarian cancer cells." (PMID 32312965, 2020). "We measured the expression levels of COL11A1 and FAO enzymes in ovarian cancer cells by RT-PCR and Western blotting." (PMID 32312965, 2020). "These in vivo results were reinforced by the in vitro findings from a panel of eight ovarian cancer cell lines in which SC66 treatment suppressed cell proliferation and invasion, and regulated COL11A1 to overcome chemoresistance and promote cell apoptosis." (PMID 30975980, 2019). "Similar to the mesenchymal subtype from the original TCGA study of ovarian cancer, S‐ECM shows upregulation of genes such as COL5A2, COL1A1, COL3A1, THBS2, COL11A1, COL6A3, and MMP2 that are involved in epithelial‐to‐mesenchymal transformation (EMT) processes, metastasis, and chemoresistance." (PMID 36637997, 2023). "COL11A1 mediates the upregulation of p-Sp1 and finally induces the increased release of TGF-β3 and interleukin-6, thus promoting the proliferation and migration of ovarian cancer cells." (PMID 35813831, 2022). "In ovarian cancer, PRRX1 enhances tumor progression and resistance to chemotherapy and radiotherapy by activating COL11A1, and miR-335 inhibits the invasion and migration of ovarian cancer cells by inhibiting the expression of COL11A1." (PMID 36160004, 2022). "For example, many TGF-β signaling-related genes derived from CAFs play important roles in the crosstalk between fibroblasts and ovarian cancer, including periostin (POSTN), collagen type XI alpha 1 (COL11A1), collagen triple helix repeat containing-1 (CTHRC1), and versican (VCAN)." (PMID 35681617, 2022).
ovarian carcinoma (continued). "Although the link between HSP27 and cancer cell chemoresistance has been clearly established, our study demonstrates HSP27 is a novel mediator of COL11A1-driven cisplatin resistance and provides a potential mechanism of how HSP27 becomes upregulated in ovarian cancer." (PMID 34638339, 2021). "After identifying HSP27 as a novel downstream molecule of COL11A1 that promotes cisplatin resistance, it was necessary to test whether HSP27 also regulates FAO in ovarian cancer cells." (PMID 34638339, 2021). "We show that COL11A1 upregulates both fatty acid synthesis and oxidation predominantly through DDR2-Src-Akt-AMPK dependent signaling to inhibit cisplatin-induced apoptosis in ovarian cancer cells." (PMID 32312965, 2020). "Inhibition of fatty acid synthesis downregulates FAO despite the presence of COL11A1, suggesting that fatty acid synthesis might be a driver of FAO in ovarian cancer cells." (PMID 32312965, 2020). "In contrast, COL11A1 does not change glycolysis, yet preferentially upregulates fatty acid metabolism to promote cisplatin resistance in ovarian cancer cells." (PMID 32312965, 2020). "To further validate whether COL11A1 increases the FAO rate in ovarian cancer cells, we supplemented a long-chain fatty acid substrate, palmitate, to ES2 cells cultured on COL11A1 extract, and measured OCR using the Seahorse XF analyzer." (PMID 32312965, 2020). "Furthermore, the enhanced expression of COL5A1, COL11A1, and VCAN through regulation of TGF-β1 signaling was identified in ovarian cancer metastasis." (PMID 33026975, 2020). "Similarly, etomoxir treatment significantly reduced COL11A1-induced NADH levels in OVCAR3 cells, suggesting that COL11A1 increases ATP and NADPH production through FAO in ovarian cancer cells." (PMID 32312965, 2020). "To determine whether the effectors of the COL11A1 signaling, Src, Akt, and AMPK, also play a role in upregulating FASN in ovarian cancer cells, we blocked these signaling molecules using pharmacological inhibitors and measured the expression of FASN." (PMID 32312965, 2020). "The expression of COL11A1, COL5A1 and COL6A2 is related to overall survival (OS) rate in patients with high-grade serous ovarian cancer, and their increased expression may also lead to the resistance of ovarian cancer cell lines." (PMID 36505882, 2022). "To determine whether HSP27 expression and phosphorylation is upregulated by COL11A1 in vivo, we intraperitoneally injected nude mice with PBS or COL11A1 extract followed by injection of A2780 human ovarian cancer cells, which were then later challenged with cisplatin treatment." (PMID 34638339, 2021). "Notably, the binding of COL11A1 to both α1β1 integrin and DDR2 to activate the Src-phosphatidylinositol 3-kinase (PI3K)/AKT-NFκB signaling pathways induced the expression of three cisplatin-induced apoptosis inhibitors in ovarian cancer." (PMID 31521169, 2019). "Interestingly, our report demonstrated that anticancer drugs, such as cisplatin and paclitaxel, preferentially induce COL11A1 expression in the cisplatin-resistant ovarian cancer cell line A2780CP70, but not in its cisplatin-sensitive counterpart, the A2780 cell line." (PMID 35847935, 2022). "Interestingly, this group did not see an induction of the pro-survival proteins BIRC2, BIRC3, nor Bcl-2 when COL11A1 was overexpressed in A2780 and ES2 ovarian cancer cell lines, nor a reduction of these proteins when COL11A1 expression was knocked down in A2780CP70 ovarian cancer cell line." (PMID 33668097, 2021). "Here we showed that COL11A1, and not type I collagen, upregulates total and phosphorylated HSP27 in ovarian cancer cells." (PMID 34638339, 2021). "Taken together, these results suggest that COL11A1, but not type I collagen, upregulates the FAO process in ovarian cancer cells." (PMID 32312965, 2020).
ovarian carcinoma (continued). "Our study showed that a blockade of CD36, a fatty acid transporter known to drive FAO37, did not affect FAO in the presence of COL11A1, suggesting that CD36-mediated fatty acid uptake only minimally supports FAO in ovarian cancer cells that reside in the COL11A1-rich microenvironment." (PMID 32312965, 2020).
breast carcinoma (47 papers, 2011 to 2025). "Our findings indicate that the dynamic alterations in COL11A1 gene expression are intricately involved in both the carcinogenesis and development of breast cancer, underlining the potential of COL11A1 as a significant diagnostic and prognostic marker." (PMID 39845732, 2025). "COL11A1 overexpression has been associated with distinct mechanisms of therapeutic resistance in breast cancer." (PMID 41462920, 2025). "The changes in COL11A1 mRNA levels emerge as a promising diagnostic and prognostic marker for breast cancer, effectively reflecting the progression of the disease." (PMID 39845732, 2025). "We then consolidated an OPN pathway and upregulated gene signatures from our findings (Spp1, Timp3, Col11a1, Mmp9, Mmp2, Fn1, Cd44, and Il-4) to interrogate how their predicted activity is associated with relapse-free survival in breast cancer patients." (PMID 39448577, 2024). "In this study, we report that high collagen type XI alpha 1 (COL11A1) expression was associated with poor therapeutic response and prognosis in breast cancer patients treated with tamoxifen." (PMID 38806505, 2024). "As in breast cancer, the aim of this work in colon cancer was to determine the diagnostic utility of COL11A1 in small samples where microinfiltration is difficult to identify." (PMID 37760937, 2023). "The analysis results of the two data consistently showed that high expression of COL11A1 was significantly associated with poor OS in breast cancer patients." (PMID 36160004, 2022). "As shown, decreased B cells and CD4+ memory T cell infiltration or increased macrophage and basophil infiltration associated with high COL11A1 expression suggest poor prognosis in breast cancer patients." (PMID 36160004, 2022). "More importantly, we further found that COL11A1 was associated with the prognosis of breast cancer patients, possibly due to its involvement in the regulation of tumor immunosuppression." (PMID 36160004, 2022). "Another study unraveled that COL11A1 expression was found in fibroblasts associated with breast cancer and played a vital role in the metastasis of tumor cells." (PMID 31938021, 2020). "Some genes in this list have been reported to be associated with the process of cancer metastasis, e.g., COL11A1 has been identified as a remarkable biomarker for carcinoma progression and metastasis in breast cancer and serous ovarian cancer." (PMID 28678795, 2017). "This study was the first to assess the differential expression of COL11A1 A and E splice variants in breast cancer tissues and in cancer in general." (PMID 26466668, 2015). "When 90 breast cancer tissues were studied, only A and E variants were encountered while the general COL11A1 transcript was present in all samples." (PMID 26466668, 2015). "Additionally, COL11A1 is associated with breast cancer metastasis and has been used as a diagnostic marker to distinguish between invasive and non-invasive breast cancer." (PMID 39857819, 2025). "High COL11A1 expression strongly associated with poor prognosis in breast cancer." (PMID 39845732, 2025). "Finally, COL11A1 has been associated with poor survival, chemoresistance, and recurrence in breast cancer, suggesting a potential role in TNBC progression." (PMID 40867231, 2025). "Within this context, COL11A1, a fibrillar collagen overexpressed in pathological conditions, has attracted attention due to its association with tumor progression, therapeutic resistance, and prognosis across multiple cancer types, including breast cancer." (PMID 41462920, 2025). "Previous bioinformatics analysis has demonstrated that COL5A2, COL10A1, and COL11A1 may be used as a diagnostic or prognostic biomarker for tumors such as gastric cancer, breast carcinoma, and non-small-cell lung cancer." (PMID 37082197, 2023). "Circulating COL11A1 expression is elevated in plasma samples of breast cancer patients and may be helpful in the diagnostic evaluation of suspicious breast nodules." (PMID 36246404, 2022).